SDC1 (syndecan 1)
Diseases named in the same sentence as SDC1 in open-access papers (continued):
Sharing a sentence is not in itself a finding about the gene and the disease.
cancer (continued). "SDC1 is expressed most strongly in the cancer‐in‐situ regions in the MCIST plot, corresponding also to increased pseudotime positioning just before the highest values where full invasiveness has begun." (PMID 40948400, 2025). "Conversely, Syndecan-1 detection predominates in poorly formed gland morphologies and is reduced in lower-grade cancers, creating a biomarker system that directly aligns with Gleason grading." (PMID 41465218, 2025). "Shed syndecan-1, particularly in cancer, promotes tumor growth and metastasis, while syndecan-2 can inhibit angiogenesis by reducing endothelial cell migration 241,242." (PMID 41281748, 2025). "The results showed that with changes in SDC1 expression, fibroblasts, macrophages, and cancer cells all showed different differentiation nodes." (PMID 41209699, 2025). "Utilizing this approach, we sought to elucidate the potential evolutionary sequence between cell states of fibroblasts, macrophages, and cancer cells by leveraging the continuity feature of SDC1 gene expression." (PMID 41209699, 2025). "A novel function of syndecan-1 includes nuclear translocation in cancer cells, where it affects gene transcription by modulating enzymes such as histone acetyltransferase (HAT), promoting tumorigenic gene expression." (PMID 41281748, 2025). "SDC1 and SDC4 have been associated with cell signaling and functional properties, while also holding prognostic value in various cancer types." (PMID 41228316, 2025). "Changes in the expression of these components, such as syndecan-1, directly impact cancer progression, making them valuable biomarkers and potential therapeutic targets." (PMID 39728992, 2024). "Cell-cell communication analysis reveals SDC1 as an important target on cancer cells interacting with ACSL4+CAFs." (PMID 39238647, 2024). "We performed cell-cell communication analysis between cancer cells and a few specific ferroptosis-related TME cell subpopulations, and the results yielded that SDC1 was a crucial target associated with ACSL4+CAFs." (PMID 39238647, 2024). "Another action of syndecan 1 and other HSPGs is the formation of fibronectin and collagen 1 fibers, which enable cancer cells to migrate." (PMID 39334952, 2024). "As a result, SDC1-LB-MSN-GEM/HNK combined advantages of both GEM and HNK and simultaneously targeted and eliminated pancreatic cancerous and cancer-associated stromal cells." (PMID 38338418, 2024). "OVOL1 and SDC1 were also related to activation of several cancer related pathways, such as NOTCH, WNT signaling pathways and focal adhesion." (PMID 37950222, 2023). "Drug-sensitivity analysis using the Genomics of Drug Sensitivity in Cancer (GDSC) database showed that SDC1 expression was closely related to existing drugs." (PMID 38048216, 2023). "CSPG4 and SDC1 are also essential to cell surface adhesion molecule contributing to cancer progression by promoting cell proliferation, metastasis, invasion, and angiogenesis and is associated with relapse through chemoresistance." (PMID 36746966, 2023). "Altered interaction of syndecan-1 and integrin αv β3 caused by YKL-40 can affect cell adhesion provided by integrins, increasing the metastatic potential of cancer cells." (PMID 37185706, 2023). "HSPGs, including the SDC1 and SDC4 proteins, have been linked to metabolism, infectious diseases and cancers including BC." (PMID 36152082, 2023). "In PCa, Syndecan-1 expression has been observed in tissue samples with advanced cancer morphologies, including poorly formed glands, nests and cords of cells, and cribriform and intraductal carcinoma patterns." (PMID 37371647, 2023). "We have recently shown that surface syndecan-1 is over-expressed on cerebrospinal fluid (CSF) floating cancer cells of patients with BC leptomeningeal metastasis." (PMID 36088392, 2023).
cancer (continued). "The critical role of SDC1 in promoting tumorigenesis and metastasis has been increasingly recognized in various cancer types 8-10, implying a promising potential of utilizing SDC1 as a novel target for cancer therapy." (PMID 37441590, 2023). "Using tissue microarrays, we demonstrated by immunohistochemistry that sortilin was highly expressed in low-grade cancer, while syndecan-1 was upregulated in high-grade disease." (PMID 37596305, 2023). "Further, COL1A1, COL1A2, COL6A1, COL6A3, and SDC1 were upregulated in late-stage compared with early-stage patients in four cancer types." (PMID 38002057, 2023). "To efficiently capture these plasma ofCS glycans, we optimized an ELISA assay with different capture and detection pairs (anti- CD44, -CSPG4, -SDC1, and rVAR2), and tested their performance of detection ofCSPGs in plasma of malignant tumor patients." (PMID 36746966, 2023). "The colocalizations of the ofCS with their core proteins (CD44, CSPG4, and SDC1) were detected on various cancer cells by immunofluorescence analysis." (PMID 36746966, 2023). "Numerous studies on different cancer types have characterized SDC1 as a key factor in EMT, as its repression in most carcinomas favors EMT." (PMID 36358747, 2022). "SDC1 is a type I transmembrane glycoprotein mainly expressed in epithelial cells, and disorder of SDC1 expression leads to cancer development by promoting cell proliferation, metastasis, invasion, and angiogenesis." (PMID 35432485, 2022). "In cancer, Sdc-1 is involved in the regulation of cell migration, cell-cell and cell-matrix interactions, growth-factor, chemokine, and integrin activity, and in the regulation of protease activity." (PMID 35155241, 2022). "For example, the Syndecan-1 pathway, which we found to be associated with gut microbial taxa only in CRC, has been previously shown to regulate the tumorigenic activity of cancer cells." (PMID 35577971, 2022). "Both syndecan-1 and syndecan-4 cooperate with integrins and receptor tyrosine kinases to regulate cancer cell-stroma communication." (PMID 35378690, 2022). "Biomarkers of cancer such as overexpression of SDC1 and constitutive activation of ErbB2/HER2 were also identified." (PMID 36009225, 2022). "SDC1 mediates cell binding, cell signaling and cytoskeletal organizations, and it can have a different impact according to cancer type." (PMID 35328227, 2022). "Sdc-1 plays an important role in the progression of different types of cancers by regulating the hallmarks of cancer such as proliferation, angiogenesis, apoptosis, invasion, and metastasis." (PMID 35155241, 2022). "Syndecan-1 plays a key role in the modulation of cancer cell proliferation and invasion, inflammation, and matrix remodeling." (PMID 34206469, 2021). "Due to its multiple roles in cancer pathophysiology, SDC-1 is an appealing molecular target for therapeutic strategies." (PMID 35118073, 2021). "In conclusion, SCGB3A2 uses the machinery of the pyroptotic cell death for the elimination of SDC1/CASP4-positive human cancer cells." (PMID 33452234, 2021). "Together, this provides further explanation for impaired angiogenesis upon Sdc-1 expression ablation in cancer cells, which apparently acts in a cell context-dependent manner." (PMID 34066023, 2021). "This duality is particularly apparent in the development and progression of various cancers, because overexpression of SDC1 has been viewed as an adverse event in some tumors but beneficial in others." (PMID 33801718, 2021). "Hepatocarcinogenesis was followed up in transgenic and wild-type animals, and a six month delay in the formation of overt cancer was observed in hSDC1+/+ mice, confirming the assumption that SDC1 suppresses oncogenesis in the liver." (PMID 33801718, 2021). "Syndecan-1 is supposed to mediate macropinocytosis at the cell surface, which is involved in cancer growth and progression." (PMID 34206469, 2021).
cancer (continued). "All this highlights that although known as a cell surface HSPG, syndecan-1 can have cytoplasmic localization, and this is reported in several cancer studies." (PMID 33921767, 2021). "In recent years, a number of studies have suggested that syndecan-1 not only contributes to normal cellular biological phenomena but also plays a role in different pathological processes, including benign tumors and cancers." (PMID 31540870, 2021). "Available data have supported cell-surface binding, shedding and nuclear localization of SDC-1 to contribute to cancer progression, although study of such phenomena has remained unsystematic." (PMID 35118073, 2021). "Such a mechanism is also known for increased angiogenesis in cancer by shed SDC-1 with binding to pro-angiogenic factors such as VEGF, FGF2, insulin-like growth factor 1 receptor—IGFR1 and presenting these growth factors to their respective receptors." (PMID 33562126, 2021). "Syndecan-1 is a Janus-faced proteoglycan: depending on the type of cancer, it can promote or inhibit the development of tumors." (PMID 33801718, 2021). "The non-enzymatic activity of heparanase—known to be modulated by Sdc-1 expression—induces F3 expression in cancer cells and impacts cancer progression." (PMID 34066023, 2021). "MDK (a cytokine and growth factor with complex biological functions involved in cancer development and progression), together with its two receptors (SDC1 and GPC2) were highly expressed in the B-cells of BCP-ALL samples." (PMID 33777800, 2021). "Sdc-1 is involved in various vital processes relevant to cancer progression, such as cell adhesion, proliferation, migration, invasion, and metastasis." (PMID 34066023, 2021). "Taken together, the shed ectodomain of SDC1 acts on cancer cells and has powerful effects on their behavior in a context-dependent manner." (PMID 34113616, 2021). "In conclusion, SDC-1 is a promising biomarker that can contribute to cancer diagnosis and prognosis." (PMID 35118073, 2021). "As molecular biology and detection technology continues to advance, studies are increasingly focusing on the effects of cellular SDC-1 localization on cancer prognosis and disease phenotype." (PMID 35118073, 2021). "This lines up well with our previous study, indicating the pivotal role of Sdc-1 in regulating cancer stem cells in IBC tumors." (PMID 34066023, 2021). "Subsequent studies focusing largely on cancer mechanisms have shown that the activities of the αvβ3 and αvβ5 integrins and IGF-1R are linked and regulated by syndecan-1 (Sdc1)." (PMID 34778093, 2021). "The senescent cells overexpress syndecan-1 (SDC1), a poor prognostic factor for cancer growth, which is the result of aTGF-β acting through the Smad pathway." (PMID 33478130, 2021). "Regardless of its inhibitory or activating effects, these studies indicate that SDC1 plays a pivotal role in cancer." (PMID 35087751, 2021). "Although syndecan-1 (SDC1) is known to be dysregulated in various cancer types, its implication in tumorigenesis is poorly understood." (PMID 33801718, 2021). "SDC1 had only slightly elevated mean levels in cancer compared to controls; 9,461 pg/mL vs. 8,707 pg/mL." (PMID 33823873, 2021). "Interaction between SDC-1 and the extracellular matrix plays an essential role in cancer pathogenesis." (PMID 35118073, 2021). "This provides a clue with regard to the frequent observation that cytoplasmic syndecan-1 accumulates in many carcinomas." (PMID 33921767, 2021). "Syndecan-1, by virtue of its widespread presence and abundance in epithelia has then been of interest in a wide variety of carcinomas." (PMID 33921767, 2021). "Given that shed SDC1 in the serum is a prognostic factor in several cancers it is likely that there are several other pro-tumorigenic effects of shed SDC1 into the microenvironment that are yet to be discovered." (PMID 32760722, 2020).
cancer (continued). "MCF-7 cells, which exhibit epithelial characteristics, and MDA-MB-231, a more aggressive BC cancer cell line with mesenchymal characteristics, were used to study the role of syndecan-1." (PMID 32847060, 2020). "The results should serve as a fundament for further studies to discover the role of nuclear SDC1 in normal and cancer cells of different origin." (PMID 32664515, 2020). "Among all predicted target genes, the potential target Syndecan 1 (SDC1) acts as an important factor that participates in cancer, inflammatory diseases, and pathogen infection." (PMID 32153518, 2020). "HPSE expression strongly correlates with poor survival in BC and serum levels of shed SDC1 have been identified to be informative in regards to progression of several cancers including breast." (PMID 32760722, 2020). "Altered Sdc-1 expression has been linked to aberrant CSC function, a phenotype linked to therapeutic resistance and cancer recurrence." (PMID 32477959, 2020). "According to literature, Sdc-1 appears to affect cell viability, as Sdc-1 has been reported to prevent epithelial apoptosis and its absence in specific types of cancer results in cell cycle arrest and early apoptosis." (PMID 32701966, 2020). "Previously, Syndecan-1 was shown to modulate the cancer stem cell phenotype via the IL-6/STAT3, Notch and EGFR signaling pathways in triple-negative IBC." (PMID 32961706, 2020). "Targeting TAE dysregulation pathways, such as the heparinase/syndecan-1 axis, is a new approach to cancer treatment in the context of the role of TAEs in promoting cancer cell survival and growth." (PMID 33183286, 2020). "Syndecan-1 and -2 expression by PC cells was proposed as a useful prognostic marker for patients who presented with clinically localized cancer." (PMID 32847060, 2020). "It was observed that the more of the syndecan-1 was localized in the stroma, the less of it was found on the cancer cells." (PMID 32388727, 2020). "IL5-mediated signaling and Syndecan-1-mediated signaling enhances cancer cell migration and invasion." (PMID 32448176, 2020). "Syndecan-1 is a cell surface heparan sulfate proteoglycan and is known to have functions in cancer cell signaling, such as in multiple myeloma and breast cancer." (PMID 32331346, 2020). "In different cancer types syndecan-1 plays dynamic roles, whereby it can either suppress or promote tumor progression." (PMID 32731396, 2020). "Analyzing exosomes from A549 cancer cells expressing syndecan-1 showed an upregulation of 43 miRNAs and a downregulation of 91 miRNAs when compared to exosomes from syndecan-1 deleted cells." (PMID 32331346, 2020). "It has been shown that syndecan-1 is a modulator of the cancer stem cell (CSC) phenotype of triple-negative inflammatory breast cancer via the IL-6/STAT3, Notch, and EGFR signaling pathways." (PMID 32847060, 2020). "The heparan sulfate proteoglycan Syndecan-1 binds cytokines, morphogens and extracellular matrix components, regulating cancer stem cell properties and invasiveness." (PMID 32477959, 2020). "In this cancer type, Sdc-1 silencing promoted EMT and a stem-like phenotype and stimulated integrin signaling through FAK kinase phosphorylation." (PMID 33330449, 2020). "Changing syndecan-1 localization from surface to cytoplasm in cancers leads to lose its original function, connecting the cell to ECM." (PMID 32388727, 2020). "In the fourth and fifth week after cancer cell inoculation, glycocalyx disruption (SDC-1), endothelial inflammation (sVCAM-1, sE-sel) and increased vascular permeability (Angpt-2) were also noted." (PMID 30683749, 2019). "In the first week after cancer cell inoculation, marked glycocalyx disruption (SDC-1 and ESM-1) and notable activation of pro-inflammatory adhesion molecules [soluble VCAM-1 (sVCAM-1)] were detected." (PMID 30683749, 2019).
cancer (continued). "In the second week after cancer cell inoculation, plasma concentrations of SDC-1, ESM-1 and sVCAM-1 diminished to values observed in control animals, while plasma concentration of Angpt-2 rose from 146.17±8.31 to 228.93±8.57 pmol/ml." (PMID 30683749, 2019). "So far, Sdc1−/− knock-out (KO) mouse models revealed the participation of SDC1 in cancer cell proliferation and apoptosis, as well as in angiogenesis." (PMID 30825879, 2019). "The involvement of Sdc1 in the progression of both primary cancers was proved, as well as the involvement of Sdc1 in the development of the metastatic potential of ductal tumors when invading the axillary lymph nodes." (PMID 30151336, 2018). "Of note is that the levels of SDC1 expression differ depending on cancer types and are strikingly dysregulated in many cancer cells." (PMID 30526845, 2018). "It is supported by the fact that the epithelium of both primary carcinomas expresses the Sdc1 in exactly the same way, in 90% of cases." (PMID 30151336, 2018). "The proportion of apoptotic carcinoma cells - identified by active caspase 3 expression - was also lower in Sdc1−/− animals by 64%." (PMID 29976229, 2018). "Judging from the decreased Ki67 proliferation index seen in Sdc1−/− mice, host Sdc1 stimulates proliferation of disseminated carcinoma cells." (PMID 29976229, 2018). "Overall, these data are consistent with Sdc1 in the metastatic microenvironment stimulating the proliferation of carcinoma cells." (PMID 29976229, 2018). "Syndecan-4 promotes cell adhesion, in contrast to syndecan-1, which is increased during malignancies and promotes the aggressiveness of cancer cells." (PMID 28079144, 2017). "Here, we examined SDC1 expression in datasets from The Cancer Genome Atlas and the National Center for Biotechnology Information Gene Expression Omnibus." (PMID 28422726, 2017). "SDC1 also enhanced oncogene and growth factor signaling, inhibited cancer cell apoptosis, and promoted angiogenesis." (PMID 29230082, 2017). "Knockdown of SDC1 with siRNA in MDA-MB-231 cells reduced cancer stem cell pools significantly and lowered IL6 and IL6R levels which resulted in a decrease in STAT3 signaling." (PMID 29230082, 2017). "What's more, ionizing radiation-mediated premature senescence and paracrine interactions with cancer cells colud enhance the expression of syndecan 1 in human breast stromal fibroblasts." (PMID 27901488, 2017). "The best illustration of the functional consequence of this interaction in cancer is given by myeloma cells which overexpress syndecan-1." (PMID 27279652, 2016). "In this way, OPG binds to glycosaminoglycans and proteoglycans such as syndecan-1 through its heparin-binding domain with a strong influence on cancer cell development." (PMID 27279652, 2016). "Multiple clinical trials are currently evaluating the safety and efficacy of pharmacologically targeting SDC1 in different types of cancer." (PMID 26293675, 2015). "Based on the numerous roles in cancer pathology, SDC1 is an attractive molecular target for therapeutic strategies." (PMID 26293675, 2015). "Deregulation of SDC1 contributes to cancer progression by promoting cell proliferation, metastasis, invasion and angiogenesis, and is associated with relapse through chemoresistance." (PMID 26293675, 2015). "The levels of soluble SDC1 in the sera of healthy persons are relatively low compared to levels in cancer patients." (PMID 26293675, 2015). "The results indicated that all-trans retinoic acid inhibited lung tumor development and reduced SDC1 expression in cancer cells." (PMID 26293675, 2015). "The value of SDC1 as a prognostic marker for specific cancer types has been extensively evaluated in solid and hematological cancers." (PMID 26293675, 2015). "Zoledronic acid (Zometa®) is a third-generation bisphosphonate that inhibits SDC1 expression in cancer cells in a dose-dependent manner." (PMID 26293675, 2015).